TREM2 (triggering receptor expressed on myeloid cells 2)
Diseases named in the same sentence as TREM2 in open-access papers (continued):
Sharing a sentence is not in itself a finding about the gene and the disease.
tumor (continued). "Here the authors show that spatially organized and self-propagating TREM2+ tumor associated macrophages promote Ly6D- tumor cell proliferation via secretion of oncostatin M." (PMID 37164949, 2023). "This demonstrates that TREM2 deficiency impacts the restructuring of the myeloid cell compartment within a tumor." (PMID 36119485, 2022). "These CD8+ T cells were deemed activated based on PD-1 expression and tumor growth was restrained in the TREM2 deficient mice." (PMID 36119485, 2022). "In conclusion, our findings revealed that TREM2 was significantly expressed in microglia and macrophage cells and was intimately associated with the tumor immune microenvironment." (PMID 36713360, 2022). "Cluster 8 demonstrated the greatest reduction following treatment compared with control and scored high for macrophage and M2 module scores, as well as expression of Trem2, previously associated with immunosuppressive activity and increased tumor growth." (PMID 35260537, 2022). "In the current study, we found that TREM2 was associated with the PTC tumor microenvironment and further confirmed that the TREM2 expression was upregulated in PTC tissues." (PMID 36438899, 2022). "Subcutaneous MCA/1956 tumors in mice deficient for TREM2 displayed an increase in CD8+ T cells as a percent of all tumor infiltrating T cells compared to wild-type mice." (PMID 36119485, 2022). "CIBERSORT research revealed a link between a higher TREM2 expression level and the enrichment of tumor-associated macrophages, especially M2 subtype." (PMID 36713360, 2022). "Studies have used scRNAseq to understand how TREM2 deficiency impacts the myeloid compartment in the TME as well as tumor progression." (PMID 36119485, 2022). "Consistent with our findings, TREM2-deficient mice showed reduced tumor growth, along with decreased Mreg and increased TAM population frequencies." (PMID 35746551, 2022). "This specific TREM2 mAb, PY314, is a depleting antibody designed to deplete tumor associated macrophages expressing TREM2." (PMID 36119485, 2022). "On the other hand, patients with advanced tumor grade, pathologic stage, and T stage were significantly associated with increased accumulation of TREM2+ LAM-like cells." (PMID 35359989, 2022). "A histological examination revealed that this population (defined as CD68/CD163+C1Q+TREM2+) was present only in tumor tissues and was significantly associated with post-surgical disease recurrence." (PMID 35746551, 2022). "There are recent data on the expression of TREM2 in various types of macrophages, such as tumor-associated macrophages (TAMs) and liver macrophages." (PMID 36361908, 2022). "This suggests that TREM2 expression in tumor-specific macrophages is associated with a pro-tumorigenic environment." (PMID 36119485, 2022). "TREM2 emerged as a specific marker of TAMs, consistent throughout different human cancers and tumor models, and strongly associated with immunosuppression." (PMID 35746551, 2022). "TREM2 deficiency was associated with increased acute liver damage, increased inflammatory mediators, and less fibrosis, and yet increased tumor development and progression." (PMID 35746551, 2022). "Further, TREM-2 is expressed by tumor-associated macrophages (TAMs) in various tumor types and plays an important role in tumor immunity." (PMID 36012120, 2022). "Herein, we systematically investigated the single-cell transcriptomes of human HCC tissues and found that TREM2 was predominantly expressed by a macrophage subpopulation enriched in tumor tissues that resemble lipid-associated macrophages (LAMs)." (PMID 35359989, 2022). "The expression of TREM2 was associated with the depth of tumor invasion (P < 0.05), TNM stage (P < 0.05), histologic grade (P < 0.0001), histologic type (P < 0.05), and anatomic subdivision (P < 0.01) in 393 patients." (PMID 33976737, 2021).
tumor (continued). "TREM2 expression was higher in GC cell lines and was remarkably associated with tumor invasion depth, TNM stage, histological grade, histological type, anatomic subdivision, and Helicobacter pylori state." (PMID 33976737, 2021). "TREM2 affects the prognosis and clinical phenotype of tumors through its role in tumor-associated macrophages (TAMs) and myeloid-derived suppressor cells (MDSCs)." (PMID 33679809, 2021). "Trem2 deficiency and anti-TREM2 mAb were responsible for changes in the tumor-infiltrating macrophages: CX3CR1+ and CD206+ macrophage subsets declined, while other subsets were induced." (PMID 33381508, 2020). "Trem2 deficiency showed alterations in macrophage populations and an increase of tumor-infiltrating CD8+ T cells expressing PD-1." (PMID 33381508, 2020). "Using an integrated technology for single-cell RNA-sequencing and intracellular protein measurements, A recent paper published in Cell provides evidence that TREM2 was identified as a marker for tumor-associated macrophages (TAMs) and monocytes." (PMID 33037186, 2020). "Survival analysis showed that TREM2 deficiency in tumor tissues was associated with a shorter survival and higher risk of recurrence in HCC patients." (PMID 30683932, 2019). "TREM2 expression in tumor was significantly associated with overall survival (OS) (P = 0.0013) and time to progression (TTP) (P = 0.0006, respectively)." (PMID 30683932, 2019). "In line with a recent report that CXCL9 and SPP1 indicate tumor-associated macrophage polarity in human cancers, Cxcl9 expression was significantly higher in Trem2− macrophages, whereas Spp1 expression was significantly upregulated in Trem2+ macrophages." (PMID 39838454, 2025). "Additionally, TREM2+TAMs have been identified in the TME of multiple tumor types and are associated with patients who exhibit resistance or non-responsiveness to ICB treatment." (PMID 40670983, 2025). "Additionally, TREM2 expression has been linked to tumor mutational burden, microsatellite instability, and the infiltration of immune cells across multiple cancer types." (PMID 40691204, 2025). "Most tumor‐associated macrophages were Mo‐macs, which expressed high levels of Trem2." (PMID 40470646, 2025). "Additionally, two distinct immunosuppressive subtypes have been identified—one heavily infiltrated with suppressive immune cells, and another characterized by alternative tumour-supportive niches, such as TREM2+ macrophages and tumour-associated fibroblasts." (PMID 40332145, 2025). "Importantly, high infiltration of immunosuppressive TREM-2+ TAMs has been substantially associated with advanced tumor progression and suboptimal ICB responsiveness in NSCLC patients." (PMID 41023740, 2025). "Additionally, TREM2 has been identified as a marker of tumor-associated macrophages in various tumor types and influences tumor progression by modulating signaling pathways that govern cellular proliferation and metastasis." (PMID 41300781, 2025). "Addition of CD137 agonist increased abundance of clonally expanded CD8+ T cells and increased immunosuppressive TREM2 signaling in tumor associated macrophages (TAMs), identified by comparison of ligand-receptor networks, corresponding to changes in metabolism and ECM interactions." (PMID 39811671, 2025). "Cellchat analysis revealed that TCR+ Macrophages displayed the closest interaction with CD4+ T cells in tumor tissues from responsive patients, whereas TREM2+ Macrophages were predominantly associated with CD4+ T cells in tumor tissues from non-responsive patients." (PMID 38948071, 2024). "TREM-2 is overexpressed on tumor-associated macrophages (TAMs) and plays a role in tumorigenesis." (PMID 39737196, 2024). "In the context of HCC, TREM2 expression influences the infiltration and function of tumor-associated macrophages (TAMs) and myeloid-derived suppressor cells (MDSCs), which are pivotal in mediating tumor immunity and sculpting the inflammatory landscape of the TME." (PMID 39697329, 2024).
tumor (continued). "Similarly, in eCRSwNP, FN1 activated tissue-resident macrophages were observed to interact with basal EpCs via TREM2, which is a marker of tumor-associated macrophages." (PMID 38444858, 2024). "To investigate whether the specificity of TREM2 in NcDase deficient BMDMs is induced by tumor derived sphingolipids, we incubated BMDMs with TCM or ceramide." (PMID 38302493, 2024). "Similarly, a phagocytosis assay between mouse peritoneal macrophages or human monocyte-derived macrophages and tumor cells showed that TREM2 deficiency/blockade or tumor cell-CM treatment reduced the phagocytosis rate." (PMID 39135069, 2024). "Resident LAM-APOC1 was expressed both in the tumor and juxta-tumor area, strongly associated with CD8+ T cells and T-regs, while LAM-STAB1 was mostly expressed in the tumor and had a high level of TREM2 and IL-1B, suggesting their monocytic origin associated with poor prognosis." (PMID 39104525, 2024). "Moreover, survival analyses revealed that TREM2 deficiency prolonged the survival time of tumor-bearing mice, and combination treatment with GB1107 considerably improved their lifespan." (PMID 39135069, 2024). "Similarly, ELISA results showed increased granzyme B and perforin in the tumor-grinding fluid of TREM2-deficient mice, which were further enhanced by GB1107 treatment." (PMID 39135069, 2024). "Trem2 is a transmembrane receptor protein that is frequently associated with immune cells (e.g., microglia, macrophages) but is also known to be overexpressed in many cancer cells, where it can regulate both proliferation and tumor cell migration." (PMID 38631901, 2024). "More, TREM2 has been identified as an immunosuppressive marker in tumor-associated macrophages." (PMID 37198381, 2023). "However, recent studies on T CD8 + cancer infiltration indicate that the deficiency of tumor associated macrophages (TAMs) positive for TREM2 is associated with a stronger cytotoxic T cell activity and a higher responsivity to anti PD-1 immunotherapy." (PMID 36865548, 2023). "Research has shown that targeting TREM2 on tumor-associated macrophages enhances immunotherapy." (PMID 37744272, 2023). "Anti-inflammatory TAM markers (TREM2 and CD32a) are linked with tumour hypoxia (HIF-1α)." (PMID 37324244, 2023). "Besides, APOE+TREM2+ macrophages were considered as tumor associated macrophages which were enriched in tumors from patients who recurred following surgery, suggesting the potential immune modulating function of APOE." (PMID 37380987, 2023). "In addition, recent studies suggested that Trem2 is a potential therapeutic target to modulate immunosuppressive tumor-associated macrophages." (PMID 35933399, 2022). "However, the combination of anti-PD1 and TREM2-deficiency or TREM2 blockade with the 178 mAb led to a 100% tumor rejection." (PMID 35746551, 2022). "Recent studies have shown that TREM2+ macrophages are the main subsets of tumor-associated macrophages (TAMs) that mediate immune suppression and resistance to immunotherapy, confirming that targeting immune checkpoint molecules on T cells is not the only way to attenuate T cell dysfunction." (PMID 35972800, 2022). "By probing associations between TREM2 and tumor mutation burden, immune scores, tumor stage, DNA methylation, and infiltration of immune cells the investigators highlight the heterogeneity among tumor types." (PMID 36119485, 2022). "Recently, attention has been focused on TREM2-expressing tumor-associated macrophages (TAMs)." (PMID 35746551, 2022). "Hence, TREM2 targeting represents a new promising approach for cancer treatment that is based on reprogramming of tumor-associated macrophages to reshape anti-tumor immunity and overcome resistance to current therapies." (PMID 35746551, 2022). "Interestingly, apolipoprotein E (ApoE) is a Trem2 ligand and both Trem2 and ApoE are expressed by a subpopulation of tumour-associated macrophages." (PMID 34794433, 2021).
tumor (continued). "Interestingly, they found that both, mice deficient for TREM2, or antibody-mediated blockade of TREM2 signaling, resulted in delayed tumor growth." (PMID 34539650, 2021). "Then, the authors revealed that TREM2 deficiency could modify the TME in a manner that facilitated partial control the growth of tumor by CD8+ T cells." (PMID 34539652, 2021). "TREM2 protein loss gradually increased dependent on the tumor grade from stage II to stage IV." (PMID 31489935, 2019). "We observed that TREM2 levels correlated with pathological characteristics including BCLC stage, tumor size, tumor encapsulation, vascular invasion and tumor differentiation, suggesting that TREM2 may be associated with HCC progression." (PMID 30683932, 2019). "Furthermore, we found that the tumor suppressor effects of TREM2 were associated with Wnt/β-catenin and extracellular signal-regulated kinase (ERK) signaling." (PMID 31489935, 2019). "The interest in the TREM2 pathway in neuro-oncology lies in its dual role: on the one hand, activation of TREM2 can limit chronic inflammation and associated tissue damage; on the other hand, its modulation can influence the antitumor immune response and the plasticity of the tumor microenvironment." (PMID 40864821, 2025). "Moreover, an expanding body of evidence implicates TREM2 in the dynamics of tumor-associated macrophages (TAMs) and myeloid-derived suppressor cells (MDSCs), which conspire to forge an immunosuppressive tumor microenvironment, thereby influencing tumor progression and outcomes." (PMID 40552184, 2025). "Therefore, TREM2, which acts as an immunosuppressive factor, may induce a chronic immunosuppressive state in tumor-associated macrophages." (PMID 39838454, 2025). "Rasmussen and Etzerodt found that the combination between TREM2 and its ligand could promote tumorigenesis, progression, and the high expression of tumor-associated macrophages, implying that TREM2 was a key molecule in the progression of the tumor." (PMID 36741909, 2023). "However, the mechanism by which TREM2 deficiency impacted the fate of tumor macrophages remains unclear." (PMID 36359228, 2022). "The TREM-2 molecule has an anti-inflammatory effect, promotes phagocytosis, and is associated with Th2 immunity and cell-mediated immune suppression that could potentiate the tumor growth." (PMID 32684831, 2020). "While this study tackled several limitations of anti-TREM2 monotherapy, more attention is needed towards clinically relevant immunotherapy barriers in therapy-refractory tumour settings." (PMID 41562407, 2026). "Our findings highlight the pivotal role of TREM2+ TAMs in driving GC progression and shaping an immunosuppressive tumor microenvironment." (PMID 41253786, 2025). "TREM2+ macrophages exhibited a biphasic pattern, increasing during precancerous progression, but decreasing after tumor formation." (PMID 41246350, 2025). "By targeting TREM2, it is possible to attenuate the immunosuppressive capacity of M-MDSCs, enhance the body’s anti-tumor immune response, and ultimately improve the prognosis of DLBCL patients." (PMID 40242752, 2025). "Genetic deletion of TREM2 in human and mouse myeloid cells enhances interferon-gamma-induced activation, promotes pro-inflammatory polarization, and increases anti-tumor activity." (PMID 40427130, 2025). "By combining anti-PD-1 with anti-LAG3/CTLA4/TREM2, up to 100% tumor eradication was achieved in MMRd CRC and remarkably, in >70% in MMRp CRC." (PMID 40027748, 2025). "This transfer reprogrammed TAMs from anti‐tumor CD5L+ to pro‐tumor TREM2+ phenotypes, increasing CCL18 secretion, reducing phagocytic activity, and impairing CD8+ T cell proliferation." (PMID 40552574, 2025). "In MMRd tumors, resistance following anti-PD-1 treatment is driven by the expression of TIM3, LAG3, CTLA4, and TIGIT by TILs, as well as tumor clonal selection and the expression of TREM2, CSF1R, IFITM, TMEM176B and IL1B by myeloid cells." (PMID 40027748, 2025).
tumor (continued). "For example, ECM-myCAF, IFNαβ-myCAF, and TGFβ-myCAF clusters co-localize with immune cells such as TREM2+ tumor-associated macrophages (TAM) and SPP1+ TAM within the tumor bed, while Detox-iCAF co-localizes with FOLR2+ TAM in immuno-protective niches." (PMID 40890855, 2025). "This synergy is exemplified by lenvatinib plus pembrolizumab, pointing toward a future paradigm of rational combinations—co-targeting tumor cells, specific immune resistance hubs (e.g., TREM2+ TAMs), and checkpoint pathways—to overcome resistance." (PMID 41562080, 2025). "To investigate the mechanism by which TREM2 promotes tumor immunosuppression, we performed RNA sequencing of BMDMs derived from WT and Trem2−/− mice." (PMID 39838454, 2025). "Using CellChat to investigate putative cell–cell interactions, TREM2 macrophages were identified as key mediators of tumor progression via the midkine–nucleolin signaling axis." (PMID 40507339, 2025). "In pancreatic ductal adenocarcinoma (PDAC), a tumor type typically resistant to immunotherapy, TREM2 expression defines a distinct subset of TAMs that limit antigen presentation and T cell entry." (PMID 40821795, 2025). "Targeting TREM2+ TAMs represents a promising therapeutic strategy to overcome resistance to anti-PD-L1 therapy and reshape the tumor immune microenvironment." (PMID 41253786, 2025). "To identify the materials transferred from tumor cells to macrophages, we performed enrichment analysis on scRNA‐seq data from TREM2+ macrophages and CD5L+ macrophages." (PMID 40552574, 2025). "In glioblastoma, where the microenvironment is heavily myeloid-dominated, TREM2 is expressed on both TAMs and microglia, promoting tumor-supportive inflammation." (PMID 40821795, 2025). "The combination of anti‐TREM2 treatment with immunotherapy promotes expansion of immunostimulatory myeloid subsets, enhancing the anti‐tumour activity of immunotherapy such as ICIs or CAR T‐cell therapy." (PMID 40268516, 2025). "Monocyte-derived TAMs, for example, TREM2+ TAMs, infiltrate the tumor core, whereas tissue-resident-derived TAMs, such as FOLR2+ TAMs, are predominantly located within the perivascular niche of the tumor stroma." (PMID 40427136, 2025). "The results underscore a significant elevation in TREM2 gene level within tumor tissues compared to normal counterparts." (PMID 39744236, 2025). "Hence, targeting TREM2 in tumor-associated macrophages might be a feasible therapy approach." (PMID 39744236, 2025). "In recent years, the TREM2 (Triggering Receptor Expressed on Myeloid cells 2) pathway has been identified as a new molecular axis relevant in the modulation of brain inflammation and tumor microenvironment." (PMID 40864821, 2025). "Genetic ablation or CRISPR-mediated knockout of TREM2 in preclinical models to assess the effects on macrophage function and tumor immunity; 3)." (PMID 40821795, 2025). "Previous reports have revealed that TREM2-expressing macrophages adopt an M2-like phenotype and positively correlate with tumor progression." (PMID 39744236, 2025). "scRNA-seq sub-cluster analysis identified macrophages with immunosuppressive (M2-like) traits overexpressing TREM2 and SPP1, genes linked to tumor angiogenesis and ICB therapy." (PMID 41035074, 2025). "Spatial profiling demonstrates that TREM2 or SPP1-labeled, AR-imprinted macrophages cluster near tumor nests, cancer-associated fibroblasts (CAFs), and vascular hubs." (PMID 41488638, 2025). "Our results revealed that Trem2 knockout reduced the tumor load, decreased the liver/body weight ratio, and promoted tumor cell death." (PMID 39838454, 2025). "IF staining results display that macrophages are quite abundant in tumor tissue, with all three patient specimens displaying positive staining for TREM2." (PMID 39744236, 2025). "TREM2 expression is closely related to immune cell infiltration in the tumor microenvironment, particularly in macrophages." (PMID 40242752, 2025).